CD99 (CD99 molecule (Xg blood group))
Diseases named in the same sentence as CD99 in open-access papers (continued):
Sharing a sentence is not in itself a finding about the gene and the disease.
T-cell acute lymphoblastic leukemia (4 papers, 2021 to 2024). Acute lymphoblastic leukemia of T-cell origin. "In the cold state, we found that the tumor CD99 pathway plays a strong role, and it has been shown to be a potential new target for the CAR-T therapy of T-cell acute lymphoblastic leukemia." (PMID 37120690, 2023).
breast tumor (3 papers, 2021 to 2023). "For instance, a study using a transwell-based model showed that CD99 depletion in MDA-MB-231 cells (a human breast tumor cell line) caused a two-fold enhancement of transendothelial migration activity compared to the CD99+ cells." (PMID 35565413, 2022). "We noted that Scissor+ tumor cells have interaction with macrophages and T cells through CD99 that was upregulated in breast tumor cells." (PMID 37021816, 2023).
ependymoma (3 papers, 2010 to 2026). A WHO grade II, slow growing tumor of children and young adults, usually located intraventricularly. "The presence of ependymal and perivascular rosettes, immunoreactivity for GFAP (although oligodenrogliomas may also by positive for GFAP) and absence of CD57 and CD99 expression can be helpful for the establishment of a diagnosis of ependymoma." (PMID 20849631, 2010).
epithelioid sarcoma (3 papers, 2017 to 2024). An aggressive malignant neoplasm of uncertain differentiation, characterized by the presence of epithelioid cells forming nodular patterns. "CD73 along with CD99 was identified by mass spectrometry analysis as an emmprin interacting molecule from a co-culture of cancer cells (epithelioid sarcoma cell line FU-EPS-1) and fibroblasts (immortalized fibroblasts cell line ST353i)." (PMID 31510956, 2019). "Although the expression of CD99 has been reported in several malignant neoplasias and it is not specific, the focal expression of CD99 was in keeping with previous studies highlighting CD99 staining in 25% of the epithelioid sarcomas." (PMID 28810922, 2017). "While CD99 and Bcl-2 are a common feature of SFTs, we used other markers to exclude relevant differential diagnoses, like CD31 (e.g., vascularized malignancies like spindled-cell angiosarcoma), Cytokeratin MNF116 (e.g., epithelioid sarcoma), or S100 (e.g., malignant peripheral nerve sheath tumor)." (PMID 38392213, 2024).
gastrointestinal stromal tumor (3 papers, 2014 to 2025). "The tumor cells are often positive for CD34, CD99, vimentin and BCL-2, and negative for CD117 (in gastrointestinal stromal tumors), smooth muscle actin (SMA) and desmin (in smooth muscle tumors) and S-100 protein (in nerve sheath tumors)." (PMID 25884588, 2015).
inflammatory bowel disease (3 papers, 2020 to 2025). A spectrum of small and large bowel inflammatory diseases of unknown etiology. "Raised levels of neutrophil CD99 levels were recently reported in a cohort of patients with inflammatory bowel disease, thus indicating that CD99 is directly involved to inflammatory responses." (PMID 33308282, 2020). "Therefore, CD99 expression can serve as an indicator for evaluating inflammatory bowel disease activity." (PMID 40427525, 2025). "Additionally, moieties (CD44, and CD99) involved in the lymphocyte and polymorphonuclear leukocytes trafficking and correlated positively with inflammatory bowel disease (IBD) disease activity, were also significantly decreased." (PMID 33330453, 2020).
mesothelioma (3 papers, 2010 to 2016). A usually malignant and aggressive neoplasm of the mesothelium which is often associated with exposure to asbestos. "In our case, the papillary or large cell population showed a staining pattern characteristic for mesothelioma with calretinin, cytokeratin, and CD99 positivity, while the small cell component was positive for CD99, WT1, FLI-1, and cytokeratin." (PMID 27403364, 2016). "According to immunohistochemical analysis, SFT of the pleura is positive for vimentin, CD34, CD99, and Bcl2, which are markers of mesenchymal cells; but it is negative for cytokeratin, which is found in mesotheliomas." (PMID 21958732, 2011). "Our cell cultures were strongly positive for CD46, CD47, CD56 and CD63 and were also strongly positive for some markers never described before in mesothelioma cell lines, including CD55, CD90 and CD99." (PMID 20175889, 2010). "The four MM cell cultures were also strongly positive for some markers never described before in mesothelioma cell lines, including CD55, CD90 and CD99 that may represent new markers potentially useful for the isolation of cancer stem cells from MM." (PMID 20175889, 2010).
myeloma (3 papers, 2015 to 2024). "The flow cytometry experiment showed that HuMT99/3 binds specifically to CD99-expressing myeloma cells." (PMID 39595598, 2024). "In the present work we demonstrate for the first time that two different human myeloma cell lines (H929 and U266) and, in a less degree, their conditioned media significantly downregulate CD99 expression in normal human OBs during the differentiation process." (PMID 26000312, 2015). "Moreover, the binding activity of HuMT99/3 against the full-length CD99 was confirmed using CD99-expressing myeloma cells." (PMID 39595598, 2024). "Thus, on the basis of all these findings and the intriguing role of CD99 in osteogenesis and bone pathophysiology, in this paper we analyzed the influence of human myeloma cell lines (HMCLs) on CD99 expression by hOBs." (PMID 26000312, 2015). "Not later than a few months ago, it was found that, under physiological conditions, OBs express increasing levels of CD99 during their differentiation but regarding the influence of myeloma cells on the expression of this molecule currently lack experimental evidence." (PMID 26000312, 2015). "Additionally, CD99 peptide number 6 containing a CD99 epitope of the HuMT99/3 could complete the binding activity of the HuMT99/3 on CD99-expressing myeloma cells." (PMID 39595598, 2024). "Therefore, based on the new findings demonstrating that differentiated OBs express high CD99 levels we first studied whether myeloma cells could influence the expression of this molecule and next if CD99 could be critical in the differentiation of hOBs." (PMID 26000312, 2015). "Indeed, these latter cells cocultured with the two HMCLs express less RUNX2 and COLLI amount in favor of the hypothesis that the modulation of CD99 by myeloma cells, in addition to other mechanism(s), could take part in the induction of a less differentiated OB phenotype." (PMID 26000312, 2015). "However, no data are at present available on the effect of myeloma cells on OB CD99 expression and the possible implication of CD99 in the impairment of OB differentiation in multiple myeloma (MM), a hematological B cell malignancy associated with bone disease." (PMID 26000312, 2015).
olfactory neuroblastoma (3 papers, 2016 to 2023). An olfactory neuroblastoma arising in the paranasal sinus. "Almost 100% of ESFTs stain positively with CD99, while olfactory neuroblastomas do not." (PMID 27413360, 2016). "Olfactory neuroblastomas frequently express NSE and synaptophysin and are negative for the expression of leucocyte common antigen and CD99." (PMID 31531255, 2019).
ovarian carcinoma (3 papers, 2022 to 2024). A malignant neoplasm originating from the surface ovarian epithelium. "Wu and colleagues demonstrated that CD99 is highly expressed in cisplatin-resistant ovarian cancer cells, using in vitro models (A2780/CDDP and COC1/CDDP) and ovarian tissues." (PMID 35453348, 2022). "We can summarize that simultaneous CD99 overexpression and reactivated cisplatin resistance in ovarian cancer cells suggest that CD99 can be an NRF2 downstream gene and that NRF2 can modulate cisplatin resistance by CD99 up or downregulation." (PMID 35453348, 2022). "Contrarily, CD99 is poorly expressed in cisplatin-sensitive ovarian cancer cells (A2780 and COC1) and ovarian tissues." (PMID 35453348, 2022). "Thus, CD99 overexpression results in cisplatin resistance, while CD99 knockdown sensitizes ovarian cancer cells to cisplatin." (PMID 35453348, 2022). "CD99 and PFKFB3 have been previously found to mediate metabolic reprogramming, chemoresistance, metastasis, and stemness in ovarian cancer, likely via the modulation of inhibitors of apoptotic proteins and the NF-κB signaling pathway." (PMID 38339304, 2024). "Another molecule involved in many cellular processes, including apoptosis, cell proliferation and differentiation, is CD99, a transmembrane glycoprotein coded by the MIC2 (MHC class I related antigen 2) gene that is considered a prognostic marker of ovarian cancer." (PMID 35453348, 2022).
pancreatic neuroendocrine tumor (3 papers, 2010 to 2025). Pancreatic endocrine tumor, also known as pancreatic neuroendocrine tumor (PNET), describes a group of endocrine tumors originating in the pancreas that are usually indolent and benign, but may have the potential to be malignant. "CD99, a cell surface glycoprotein, exhibited cytoplasmic positivity with paranuclear accentuation, aiding in distinguishing SPNs from pancreatic neuroendocrine tumors and other mimics." (PMID 40307756, 2025).
soft tissue sarcoma (3 papers, 2007 to 2026). A malignant neoplasm arising from muscle tissue, adipose tissue, blood vessels, fibrous tissue, or other supportive tissues excluding the bones. "Among soft tissue sarcomas, CD271, GD2, CD9, and CD90 allowed for the differential diagnosis between EES and RMS, and the CD9, CD81, CD99, and CD271 markers distinguished between OS and CDS." (PMID 34638431, 2021).
spindle cell tumors (3 papers, 2024 to 2025). "Immunohistochemical staining is also critical, with HPCs typically showing positivity for markers such as CD34, vimentin, CD99, and Bcl-2 and negativity for S100, which helps differentiate it from other spindle cell tumours." (PMID 39371697, 2024). "Immunohistochemistry frequently identifies SFT through positive staining for Vimentin, CD34, Bcl-2, and CD99, with CD34 serving as a critical marker to differentiate SFT from other spindle cell tumors." (PMID 39416460, 2024).
T-lymphoblastic lymphoma (3 papers, 2013 to 2024). The most frequent type of lymphoblastic lymphoma. "Despite its high sensitivity, CD99 is also expressed by other malignancies besides ES, such as T-lymphoblastic lymphoma and small-cell anaplastic osteosarcoma." (PMID 38459600, 2024).
teratoma (3 papers, 2016 to 2026). A non-seminomatous germ cell tumor characterized by the presence of various tissues which correspond to the different germinal layers (endoderm, mesoderm, and ectoderm). "In this patient’s case, the tissue mass had primitive neural tubes and daisy-like structures and was positive for the immunophenotypes SALL4, CD56, and CD99, confirming the diagnosis of immature teratoma." (PMID 36805679, 2023).
Autoimmunity (2 papers, 2020 to 2023). The occurrence of an immune reaction against the organism's own cells or tissues. "Although our focus has largely centered on the canonical MS protein PLP, this analysis highlights other potential proteins returned from the PEPMatch analysis that may trigger autoimmunity across a wide variety of HLA-haplotyped individuals, including CD99." (PMID 36617594, 2023). "In addition, further experiments are required to evaluate contribution of CD99 in the female bias of autoimmunity." (PMID 33297945, 2020).
Burkitt lymphoma (2 papers, 2011 to 2015). A rare form of malignant mature B-cell non-Hodgkin lymphoma. "However, among the tested cell lines, only Ramos (a human Burkitt's lymphoma cell line) expressed CD99 in a heterogeneous manner, i.e., there were CD99 expressing and non-expressing populations." (PMID 21838920, 2011).
chondrosarcoma (2 papers, 2019 to 2021). A malignant cartilaginous matrix-producing mesenchymal neoplasm arising from the bone and soft tissue. "Immunohistochemical markers like CD99 and NSE are suggested in diagnosing known primary chondrosarcoma." (PMID 31764826, 2019). "In turn, tumor cells from the only chondrosarcoma (CDS) analyzed were also positive for GD2 and CD9, in addition to CD81 and CD90, and they lacked CD10, CD58, nuMyoD1, numyogenin, CD57, and CD99 expression." (PMID 34638431, 2021).
colorectal cancer (2 papers, 2019 to 2025). A primary or metastatic malignant neoplasm that affects the colon or rectum. "We also isolated mRNA from human colorectal carcinoma and renal cell carcinoma and matching healthy tissue, but were not able to determine any conclusive CD99 isoform expression pattern." (PMID 31001265, 2019).
diabetes (2 papers, 2021 to 2026). "CD99, CLU, CD14, and SAA2 have been reported to be associated with diabetes from human serum proteins." (PMID 33995275, 2021). "Additionally, comparison of the expression level of LAMA2, MLL4, PLXDC2, CD14, CLU, CD99 and SAA2 in sera of healthy volunteers and patients with stroke and pre-diabetes suggests that LAMA2, MLL4 and PLXDC2 have better specificity for (pre-)diabetes than CD14, CLU, CD99 and SAA2." (PMID 33995275, 2021).
Endometrial stromal sarcoma (2 papers, 2024). "Endometrial stromal sarcoma was excluded in this case by negative immunostaining to CD10, ER, CD99, and Cyclin-D1 primary antibodies." (PMID 39020398, 2024).
gastric adenocarcinoma (2 papers, 2018 to 2021). "In gastric adenocarcinoma and pulmonary carcinoid tumors, the decreased expression of CD99 was strongly associated with high proliferative activity, poor survival, and a heightened risk of metastasis formation, which may be related to increased migratory/invasion cell capabilities." (PMID 34881287, 2021). "However, there is an emerging group of neoplasms, including pancreatic endocrine neoplasms, gastric adenocarcinoma and osteosarcoma (OS), in which CD99 expression is diffuse in benign diseases and absent in the malignant counterparts." (PMID 29305692, 2018).
hepatocellular carcinoma (2 papers, 2019 to 2025). A malignant tumor that arises from hepatocytes. "This study also showed that by inhibiting CD99 expression, CD8+ T‐cell function could be restored and drug resistance in patients with hepatocellular carcinoma could be reduced." (PMID 40356050, 2025). "It is noteworthy that CD99 has a positive expression in hepatocellular carcinoma, but in non-HCC cancer, it has a negative expression." (PMID 30641946, 2019).
Insulin resistance (2 papers, 2021 to 2023). Increased resistance towards insulin, that is, diminished effectiveness of insulin in reducing blood glucose levels. "CD99 was patented as a marker for insulin resistance (WO2006063733A1)." (PMID 33995275, 2021). "Although CD14, CLU, CD99, and SAA2 have been reported to be protein markers for insulin resistance, obesity, and inflammation, our data showed that they only had a modest difference in expression level between healthy and pre-diabetic sera." (PMID 33995275, 2021).
liver cancer (2 papers, 2021 to 2025). An epithelial or non-epithelial malignant neoplasm that arises from the liver. "CD99 expression levels were significantly associated with impaired function and PD‐1 expression in CD8+ T cells from human liver cancer patients." (PMID 40356050, 2025).
lung carcinoma (2 papers, 2017 to 2021). "To further analyze the impact of meprin β on CD99 shedding with regard to cell adhesion and proliferation we characterized two lung cancer associated CD99 variants (D92H, D92Y), carrying point mutations at the main cleavage site." (PMID 28903388, 2017). "Lower CD99 expression was found in lung cancers (i.e., A549, NX-value: 27.4; HBEC3-KT, NX-value: 18.1), among others." (PMID 34611477, 2021).
Malignant fibrous histiocytomas (2 papers, 2016 to 2023). "Malignant fibrous histiocytomas can occasionally be CD34 positive but are negative for CD99." (PMID 27044420, 2016).
myeloid leukemia (2 papers, 2013 to 2025). A clonal proliferation of myeloid cells and their precursors in the bone marrow, peripheral blood, and spleen. "The presence of myeloid specific markers, such as MPO, CD117, CD99 and CD34 should be helpful in making a diagnosis of myeloid leukemia first presenting in skin or cutaneous myeloid sarcoma." (PMID 23388086, 2013). "Furthermore, in functional xenograft assays, NSG mice engrafted with more immature CD99-positive CD34+CD38− AML LSCs rapidly developed fatal myeloid leukemia, whereas engraftment with CD34+CD38− CD99-negative cells resulted in normal lympho-myeloid development." (PMID 40427525, 2025).
neuroendocrine carcinoma (2 papers, 2021). A malignant neuroendocrine neoplasm composed of cells containing secretory granules that stain positive for NSE and chromogranin. "High-grade neuroendocrine carcinomas are positive for synaptophysin and chromogranin and are negative for CD-99." (PMID 34722090, 2021).
ovarian tumor (2 papers, 2020 to 2023). "In the current case, the epithelial cells of the ovarian tumors were also positive for alpha-inhibin, vimentin, and CD99." (PMID 33019452, 2020).
renal cell carcinoma (2 papers, 2019 to 2021). "Immunohistochemistry indicated FLI-1(+), CD99(+), Vimentin(+), CyclinD1(+), WT-1(+), EMA(+), Bcl2(-), Ki-67(+) 60%, CD56(-), CK(-), CD34(-), Desmin(-), and SMA(-), which suggested that renal clear cell sarcoma may not rule out renal cell carcinoma." (PMID 33859949, 2021).
spindle cell sarcoma (2 papers, 2022 to 2023). A malignant mesenchymal neoplasm composed of spindle-shaped cells. "Postoperative pathological results confirmed the renal vein leiomyosarcoma: spindle cell sarcoma, diffuse severe atypia, S-100 (-), SMA ( +), desmin ( +), CD34 (−), CD99 ( +)." (PMID 35761392, 2022). "Pathology revealed spindle cell sarcoma, diffuse severe atypia, S-100 (−), SMA (+), desmin (+), CD34 (−), CD99 (+)." (PMID 35761392, 2022).
thymic carcinoma (2 papers, 2007 to 2018). Thymic carcinoma (TC) is a type of thymic epithelial neoplasm characterized by a high malignant potential. "Helpful cytologic and immunocytochemical features in making the diagnosis of thymic carcinoma are clear-cut cytological atypia, absence of immature lymphocytes (CD1a+, CD99+), and expression of CD5 and CD70 by neoplastic epithelial cells." (PMID 17498299, 2007).
adenoma (1 paper, 2024). A neoplasm arising from the epithelium. "Given our observation that CDX2++ cells most directly reflect the progression from adenoma to cancer, we evaluated the relative abundance of candidate proteins MARCKS, CD99, and DMBT1." (PMID 39252972, 2024). "Specifically focusing on CDX2++ epithelial cells within high dysplasia regions, we suggest MARCKS, CD99, and DMBT1 as potential indicators for the transition from adenoma to carcinoma." (PMID 39252972, 2024). "To determine if protein patterns specific to CDX2- stromal and CDX2++ epithelial cells could be replicated using alternative methods, we orthogonally investigated DMBT1, CD99, and MARCKS as potential markers for adenoma stratification." (PMID 39252972, 2024).
Allergy (1 paper, 2019). An allergy is an immune response or reaction to substances that are usually not harmful. "The up-regulated genes have been previously associated with asthma; hyper-reactivity and allergy (CCR2, HRH2, PTEN); lung development and apoptosis (CHRNA7, RTKN2); and immune function (GIMAP4, GIMAP7, KLRC3 and CD99)." (PMID 30971730, 2019).
anaphylaxis (1 paper, 2021). An acute hypersensitivity reaction that occurs from exposure to an allergen. "Lacking also are studies on the roles of gap and tight junctions, and specific molecules such as nectins, PECAM and CD99 in anaphylaxis." (PMID 34360549, 2021).
anencephaly (1 paper, 2018). A rare neural tube defect during pregnancy, resulting in the absence of a large portion of the brain and skull in the fetus. "In studies on anencephaly, CD99-deficient fetuses typically demonstrated a marked impairment in thymic development, which suggests a role of CD99 in normal thymus ontogeny." (PMID 29305692, 2018).